SIRT1 (sirtuin 1)
Diseases named in the same sentence as SIRT1 in open-access papers (continued):
Sharing a sentence is not in itself a finding about the gene and the disease.
Insulin resistance (continued). "Under conditions that promote insulin resistance, such as the loss of Sirt1, it is possible that reduced ilp levels in the hemolymph could slow or prevent insulin resistance and hyperglycemia." (PMID 35435227, 2022). "Moreover, SIRT1 is related to pathogenesis of hepatic steatosis in obesity, and liver steatosis is known as one of the major insulin resistance causes." (PMID 36465704, 2022). "Decreased Sirt-1 expression may berelated to the pathogenesis of diseases associated with insulin resistance." (PMID 33687162, 2021). "Mice fed a high-fat diet have lower levels of SIRT1 in the pancreas and liver and may be associated with insulin resistance." (PMID 33546744, 2021). "SIRT1 downregulation in DM is positively associated with insulin resistance." (PMID 32364526, 2020). "Overexpression of SIRT1 and many SIRT1 activators have beneficial effects on glucose homeostasis and insulin sensitivity in diabetic animal models and humans and down-regulation of SIRT-1 in several cells and tissues have been shown to cause insulin resistance." (PMID 31579450, 2019). "In our previous study, insulin resistance in PCOS rats was associated with the AMPKα-SIRT1 pathway." (PMID 31526389, 2019). "Insulin differentially regulates adipose tissue and skeletal muscle sirtuin 1 expression in the short-term and circulating free fatty acids elevation negates these effects, which may be associated with lipid-induced insulin resistance." (PMID 29417372, 2018). "Furthermore, overexpression of miR-181a decreases levels and activity of SIRT1 protein, and causes insulin resistance in hepatic cells, which is important for development of T2D." (PMID 28605773, 2017). "Furthermore, SIRT1-deficiency intensified adipose tissue inflammation and insulin-resistance, resulting in hepatic steatosis in chronic-HFD-fed mice." (PMID 29050301, 2017). "Loss of SIRT1 has also been shown to be associated with insulin resistance." (PMID 28250026, 2017). "Both SIRT1 and p66Shc are implicated in insulin resistance in metabolic syndrome." (PMID 29340106, 2017). "In a mouse model of brain insulin resistance, intracerebral injection of streptozotocin reduces the activity of SIRT1 and causes cognitive impairment, an alteration prevented by administration of the SIRT1 activator resveratrol." (PMID 25977822, 2015). "Disruptions of peripheral clock genes mediate impairments in hepatic metabolic regulation, where a down regulation of key components of clock transcriptional machinery is associated with hepatic insulin resistance and clock gene-mediated changes in SIRT1 expression." (PMID 26562417, 2015). "Loss of SIRT1 can lead to insulin resistance and excessive hepatic lipid accumulation." (PMID 26064426, 2015). "SIRT1 downregulation by 17β-estradiol could be observed as well in human peripheral blood mononuclear cells, a cell type in which SIRT1 downregulation is associated with insulin resistance and subclinical atherosclerosis." (PMID 23734259, 2013). "Indeed, activation of SIRT1 has been implicated as potential therapy to protect against insulin resistance." (PMID 20981161, 2011). "Additionally, the mice with adipocyte-selective deletion of SIRT1 are more susceptible to diet-induced insulin resistance, which is associated with the increase in the number of adipose-resident macrophages and their polarization to the pro-inflammatory M1 subtype 77." (PMID 36632457, 2023). "However, whether VD deficiency affects gluconeogenesis and insulin resistance in the liver through regulating Sirt1 expression and AKT/FOXO1 signaling remains unclear." (PMID 35132380, 2022). "Moreover, SIRT1 protein levels, estimated by western blot analysis, were moderately lower in WBCs of T2D patients than in normal subjects, and negatively correlated with HbA1c levels, consistent with SIRT1 inactivation causing insulin resistance." (PMID 35879296, 2022).
Insulin resistance (continued). "In prediabetic patients, insulin resistance is linked to lower SIRT1 expression in subcutaneous fat and associated with higher serum inflammatory cytokine levels, thus indicating that SIRT1 in adipose tissues may have antiremodeling cardiac effects in patients with prediabetic conditions." (PMID 35469171, 2022). "Therefore, the effect of RWE including resveratrol on insulin resistance and inflammation may be associated with increased Sirt1 expression in PBMNCs." (PMID 33053742, 2020). "Also, deletion of SIRT1 in SF1 neurons caused insulin resistance in skeletal muscle." (PMID 30405528, 2018). "In addition, a high-fat diet may cause insulin resistance, lead to impaired hippocampus-dependent spatial memory and dysregulation of hippocampal SIRT1 via an epigenetic mechanism." (PMID 29340106, 2017). "In a previous study, we discovered that Res could improve insulin sensitivity and ameliorate insulin resistance in KKAy mice, which may be associated with the up-regulation of Sirt1 protein in the liver and soleus muscles and, consequently, Sirt1 and AMPK activation." (PMID 25140191, 2014). "The current study was conducted to evaluate the effect of DHA versus Vilda on insulin resistance and hyperglycemia in type 2 diabetes (T2D) rat model via SIRT1/Akt/PI3K." (PMID 41997938, 2026). "This SIRT1-induced NFκB suppression prevents the induction and the expression of inflammatory cytokines that promote insulin resistance and other complications of metabolic syndrome." (PMID 40166461, 2025). "Resveratrol activates SIRT1 and inhibits the pro-oxidant protein p66Shc, preventing insulin resistance and ovarian oxidative damage in animal PCOS models." (PMID 40694958, 2025). "In particular, SIRT1 overexpression seems to improve insulin sensitivity and to reduce insulin resistance, while its downregulation inhibits insulin signalling and glucose transport into adipocytes." (PMID 39976627, 2025). "Intriguingly, diabetic patients exhibit SIRT1 inhibition by microRNAs, triggering hepatic insulin resistance." (PMID 40422880, 2025). "This connection positions SIRT1 as a promising target for developing new approaches to treat metabolic disorders, such as insulin resistance." (PMID 40673659, 2025). "SIRT1 activation also regulates glucose homeostasis in insulin-sensitive organs, acting as a protective shield against insulin resistance." (PMID 40422880, 2025). "Understanding the binding interfaces between SIRT1 and PPARγ is critical to developing new strategies to combat insulin resistance." (PMID 40673659, 2025). "Kaempferol regulates insulin signaling pathways, ameliorates insulin resistance, and enhances glucose metabolism through interactions with NF-κB, SIRT1, and AMPK cascades." (PMID 40699849, 2025). "As vitamin D normalizes the redox state, it also mitigates oxidative stress-induced insulin resistance, and activates SIRT-1/AMPK pathways, thus improving glucose metabolism." (PMID 40004770, 2025). "We have previously reported the beneficial effect of moderate SIRT1 overexpression in protecting mice against inflammation-induced insulin resistance and impaired BAT thermogenesis." (PMID 40760244, 2025). "In fact, in patients with metabolic disorders, it has been observed that insulin resistance leads to reduced levels of SIRT1." (PMID 41228388, 2025). "For instance, downregulation of SIRT1 was found in peripheral blood mononuclear cells of patients with metabolic syndrome and insulin resistance." (PMID 40725501, 2025). "In humans, it has been reported that reduced expression levels of SIRT1 in circulating monocytes correlates with insulin resistance and metabolic syndrome and its levels also decrease in adipose tissue of obese subjects." (PMID 39980831, 2025). "Kaempferol activates sirtuin 1 (SIRT1), improving hepatic function, regulating glucose and lipid metabolism, and reducing insulin resistance." (PMID 41011683, 2025).
Insulin resistance (continued). "SIRT1 has also been associated with the ability of GLP-1 receptor agonists to improve hepatic steatosis and skeletal muscle insulin resistance." (PMID 39269759, 2024). "Mechanistically, exosomal miR-29b-3p’s downstream target for controlling insulin resistance has been found to be SIRT1 (sirtuin 1)." (PMID 39051343, 2024). "Studies indicate that GLP-1 alleviates palmitic acid-induced insulin resistance in human skeletal muscle by modulating SIRT1 and GLUT4 function through diverse molecular mechanisms." (PMID 38732190, 2024). "For instance, SIRT1 overexpression attenuated high glucose-induced insulin resistance by reducing mitochondrial dysfunction in skeletal muscle cells." (PMID 38792610, 2024). "In HepG2 cell lines, the overexpression of miR-543 was found to decrease sirtuin 1 (SIRT1) levels under high glucose stress, leading to insulin resistance." (PMID 39595541, 2024). "Using a Sirt1 conditional knockout mouse model, we found that the absence of SIRT1 in dendritic cells exacerbates weight gain, glucose intolerance, insulin resistance and respiratory change high-fat diet." (PMID 39424786, 2024). "SIRT1 also alleviates tumor necrosis factor-α (TNF-α)-induced insulin resistance partly through the anti-inflammatory effects of 3T3-L1 adipocytes." (PMID 39372420, 2024). "For instance, mice fed with a high-fat diet experienced elevated NAD+ levels, increased SIRT1 activity, enhanced mitochondrial function, and resistance to insulin resistance when treated with PARP inhibitors or when PARP1 and PARP2 were absent." (PMID 38921477, 2024). "SIRT1’s role in metabolic regulation also includes involvement in insulin resistance and glucose tolerance." (PMID 39199358, 2024). "Gluconeogenesis, glycolysis, and insulin resistance are major aspects of glucose metabolism involving SIRT1." (PMID 39372420, 2024). "Dysregulation of AMPK and SIRT1 correlates with insulin resistance as well as with other endocrine and reproductive features of PCOS." (PMID 39268230, 2024). "Insulin resistance is correlated with a decrease in SIRT1 levels in muscle tissue in type 2 diabetes 135-137." (PMID 38904020, 2024). "Suppressed glycosylation of hepatic SIRT1 leads to systemic insulin resistance, hyperglycemia, and hepatic inflammation, contributing to liver dysfunction and metabolic disorders, including diabetes." (PMID 36768465, 2023). "SIRT1 is involved in regulating inflammatory responses, gluconeogenesis, and levels of reactive oxygen species, which contribute to the insulin resistance." (PMID 36747995, 2023). "Vitamin K is involved in the activation of the AMP-activated protein kinase/sirtuin 1 pathway in the liver, which, in turn, upregulates phosphoinositide 3-kinase and glucose transporter 2 to reduce insulin resistance and fasting blood glucose." (PMID 37305083, 2023). "We found a significant inverse relationship between the expression of the SIRT1 gene and insulin levels, as well as the HOMA-IR index, which implies that SIRT1 plays a substantial role in regulating insulin resistance." (PMID 37862340, 2023). "Recent studies show that RSV administration and the accompanying activation of SIRT1 improved the health and survival of mice on a high-calorie diet by decreasing insulin resistance." (PMID 37511397, 2023). "Decreased SIRT1 contributed to TNF-α-induced insulin resistance in skeletal muscle of patients with type 2 diabetes." (PMID 37108143, 2023). "Consistent with the present findings, decreased SIRT1 expression in the SKM has been shown to be associated with lipotoxicity, glucose intolerance, and insulin resistance." (PMID 37627494, 2023).
Insulin resistance (continued). "It has been demonstrated experimentally in mice that the activation of SirT1 optimizes the organism for metabolic adaptation to insulin resistance by improving hepatic insulin sensitivity and decreasing whole-body energy requirements." (PMID 37569434, 2023). "In our study, we observed that in vWAT the increase in the SIRT-1 expression levels likely act to counteract the condition of insulin-resistance and inflammation that is established by the fructose overconsumption." (PMID 36875756, 2023). "Nonetheless, high-level athletes exhibit higher telomere length and lowered insulin resistance, correlating with higher levels of SIRT1 expression." (PMID 36678315, 2023). "Important insulin-independent signaling molecules like pAMPK and Sirt-1 promote insulin sensitivity and glucose metabolism, where they have been shown to affect insulin resistance-related variables in T2DM." (PMID 37512578, 2023). "Betanin treatment of rats with STZ-induced type 2 diabetes was associated with amelioration of insulin resistance and improved lipid profile, accompanied with modulation of the AMPK/SIRT1/NF-κB signalling pathway." (PMID 36837811, 2023). "The effect of berberine on the increase of muscle tissue, improving metabolic disorders, reducing the expression of inflammatory factors, and suppressing sarcopenia insulin resistance (IR) were reversed by SIRT1/mitophagy inhibitors." (PMID 37483428, 2023). "A previous study demonstrated that RES treatment protected high-fat diet (HFD)-induced insulin resistance (IR) rats from diet-induced IR and elevated the expression of sirtuin 1 (SIRT1) and sirtuin 3 (SIRT3), mitochondrial DNA, and mitochondrial biogenesis." (PMID 38178962, 2023). "AGEs are known to contribute to insulin resistance by down-regulation of the SIRT1 activity, an NAD+-dependent deacetylase involved in multiple physiological functions." (PMID 37259448, 2023). "SIRT1 controls insulin secretion by preserving pancreatic β-cells, improves insulin resistance, inflammation, mitochondrial function, controls oxidation of fatty acid and regulates hepatic glucose production." (PMID 37089941, 2023). "Findings also revealed that resveratrol raises the SIRT1 level in the muscle in rodents with genetically stimulated insulin resistance." (PMID 37241737, 2023). "Yunpi Heluo decoction (YPHLD) has been reported to regulate the SIRT1-FoxO1 signaling pathway in skeletal muscle, improve lipid metabolism, increase autophagy levels, and attenuate insulin resistance, potentially making it an effective treatment for diabetes." (PMID 37810881, 2023). "SIRT1 ameliorates insulin resistance by repressing protein tyrosine phosphatase 1B, a major negative regulator of insulin action." (PMID 36747995, 2023). "It has been shown that the reduction of SIRT1 expression is related to the development of insulin resistance, and increased its expression improves insulin sensitivity in skeletal muscle." (PMID 38027557, 2023). "Quercetin can alleviate insulin resistance and improve glucose metabolism by increasing SIRT1 expression." (PMID 36815979, 2023). "Enhancing NAD+ biosynthesis promotes SIRT1- and SIRT3-catalyzed reactions, improving metabolic disorders such as weight gain, insulin resistance, and dyslipidemia associated with an HFD." (PMID 36986224, 2023). "Accumulating evidence indicates that SIRT1 is involved in insulin resistance and impaired pancreatic β-cell function, the two hallmarks of T2D." (PMID 36747995, 2023). "SIRT1 reduced inflammation in adipose tissue and monocytes/macrophages and improved insulin resistance in type 2 diabetes." (PMID 37108143, 2023). "SIRT1 has been involved in insulin resistance and impaired β-cell function, which are the hallmarks of T2D." (PMID 36747995, 2023). "To summarize, treatment of inhibiting NAMPT or activating Sirt1 was able to suppress insulin resistance and renal injury as evidence by improved physiological and histopathological parameters in db/db mice." (PMID 35408818, 2022).
Insulin resistance (continued). "SIRT1 knock-out mice showed hyperglycemia and insulin resistance due to the increased hepatic gluconeogenesis and the increased intracellular ROS accumulation in multiple tissues, including the liver, adipose tissue, skeletal muscle, and spleen." (PMID 35055159, 2022). "In the prevention of type 2 diabetes, SIRT1 has become a novel therapeutic target owing to its effects on insulin resistance." (PMID 35517847, 2022). "Elevated SIRT1 concentrations were also linked to low levels of insulin, LDL cholesterol, and insulin resistance." (PMID 35055159, 2022). "Studies have shown that APS improves glucose and lipid metabolism and improves insulin resistance through the SIRT1-PGC-1α/PPARα-FGF21 signaling pathway." (PMID 35322740, 2022). "Study has reported that young liver-specific Sirt1-knockout mice suffer from hyperglycaemia and gradually develop an impaired insulin response as they grow up, finally exhibiting whole-body insulin resistance." (PMID 35132380, 2022). "DEL-1 ameliorates palmitate-induced endoplasmic reticulum (ER) stress and insulin resistance in the mouse skeletal muscle cell line C2C12 via SIRT1/SERCA2-related signaling." (PMID 36518760, 2022). "Our results showed that 1α(OH)ase−/− mice had enhanced gluconeogenesis and hepatic insulin resistance and decreased expression of Sirt1 in the liver." (PMID 35132380, 2022). "Both stimulate pathways leading to upregulation of SIRT1 to limit oxidative stress and alleviate the progression of insulin resistance." (PMID 36225477, 2022). "Mounting evidence has shown that activation of SIRT1 can improve insulin sensitivity in the liver and adipose tissues and improve insulin resistance." (PMID 35739982, 2022). "SIRT1 activation reduce insulin resistance, enhances insulin sensitivity via PGC1-α (PPARγ co-activator 1α), implementing beneficial effects in obesity and diabetes type 2." (PMID 35163422, 2022). "Mice with selective adipose tissue-disrupted SIRT1 activity show premature metabolic aging, characterized by hyperglycemia, dyslipidemia, insulin-resistance, and glucose intolerance." (PMID 36555502, 2022). "In type 2 diabetic rats, rhein ameliorates renal injury by improving insulin resistance and dyslipidemia, as well as increasing SIRT1 (Sirtuin 1) expression." (PMID 36235108, 2022). "Insulin sensitivity is enhanced by SIRT1 activation via reduction in the expression of proinflammatory genes and it attenuates the insulin resistance induced by tumor necrosis factor alpha (TNF-α)." (PMID 35163422, 2022). "In insulin resistance, atherosclerosis, and related coronary artery disease, SIRT1 is an important protective factor that inhibits the abnormal proliferation of vascular smooth muscle in atherosclerosis." (PMID 36479179, 2022). "In a prior study, we discovered that AM controls inflammation in diabetic insulin-resistant rats through mediating SIRT1 deacetylation via NF-κB p65 (K310)." (PMID 35907080, 2022). "SIRT1 improves insulin resistance by reducing OS and regulating mitochondrial biogenesis and function." (PMID 34746831, 2021). "Vitamin K1 regulates the AMPK/SIRT1 pathway, lowering insulin resistance and fasting glucose levels in diabetic mice." (PMID 33806509, 2021). "A significant decrease in fasting blood glucose levels and insulin resistance was observed after treatment with Sirt1 and Sirt3 activators." (PMID 33668369, 2021). "In recent years, SIRT1 has been found to positively regulate insulin secretion by islet β-cells, inhibit inflammation and improve insulin resistance." (PMID 34630099, 2021). "This study was designed to investigate the effect of EA on insulin resistance, SIRT1, and Fetuin-A in patients with type 2 diabetes." (PMID 33546744, 2021).